DPP4 (dipeptidyl peptidase 4)
Diseases named in the same sentence as DPP4 in open-access papers (continued):
Sharing a sentence is not in itself a finding about the gene and the disease.
Sepsis (continued). "Of note, application of DPP4 inhibitors during sepsis primarily reduced the number of genes regulated, rather than inducing other sets of genes." (PMID 40817204, 2025). "In mice, DPP4 inhibition curbed the inflammatory response to a polymicrobial sepsis resulting in a massive reduction in endothelial gene activation assoicated with preserved vascular barrier function, augmented vasopressor responses and organ integrity." (PMID 40817204, 2025). "The observed depletion of memory CD4+ T cells in patients with sepsis is consistent with the higher expression of DPP4 in these cells, supporting its potential role in sepsis progression." (PMID 40124361, 2025). "DPP4 plays key roles in glucose and insulin metabolism, as well as immune regulation—processes highly relevant to sepsis." (PMID 40124361, 2025). "DPP4 inhibition reduced white blood cell counts, especially of lymphocytes and monocytes and antagonized sepsis-induced thrombopenia." (PMID 40817204, 2025). "To further evaluate effects of DPP4 inhibition during systemic inflammation, we analyzed the impact of sitagliptin on mice subjected to severe systemic inflammation (i.e., sepsis due to polymicrobial peritonitis)." (PMID 40817204, 2025). "The results reported here suggest that the summative effect of DPP4 inhibition on surgery- and sepsis-induced systemic inflammation is mitigation of its severity." (PMID 40817204, 2025). "Analysis of endothelial transcriptome profiles in mice revealed a shift of towards lower expression levels by DPP4 inhibition during sepsis compared to untreated septic mice." (PMID 40817204, 2025). "In mice, DPP4 inhibition partially reverted sepsis-induced leukocytosis, thrombopenia and cytokine concentrations." (PMID 40817204, 2025). "A recent study showed that the risk of sepsis and pneumonia was lower in the diabetic patients who began with an SGLT2 inhibitor, compared to dipeptidyl peptidase 4 inhibitors." (PMID 38256566, 2024). "Sepsis caused by cytokine storm and direct attack of the virus through ACE-2 and dipeptidyl peptidase-4 (DPP-4), which are expressed on tubular cells, have been known as binding seats for SARS-CoV." (PMID 35337387, 2022). "The rate of sepsis- or infection-related mortality was 3.01 per 100 person-years (95% CI, 2.88-3.13 per 100 person-years) in the DPP-4 inhibitor group and 1.80 per 100 person-years (95% CI, 1.07-2.53 per 100 person-years) in the GLP-1 receptor agonist group." (PMID 35254430, 2022). "In the present study we examined the anti-inflammatory and anti-thrombotic effects of linagliptin, a DPP-4 inhibitor, on in vitro and in vivo models of sepsis." (PMID 35328486, 2022). "Our group investigated the effects of GLP-1 analogs and DPP-4 inhibitors in lipopolysaccharide (LPS)-induced sepsis." (PMID 34439423, 2021). "In LPS-induced sepsis, we performed survival studies and demonstrated that pharmacological DPP-4 inhibition or genetic deletion and administration of the GLP-1 analog liraglutide improved mortality." (PMID 34439423, 2021). "This is in accordance with previously published data reporting a lower DPP4 activity in patients with severe sepsis." (PMID 32315321, 2020). "DPP4, also known as CD26, is a co-stimulatory molecule for T-cells and has several substrates that can be involved in sepsis." (PMID 32315321, 2020). "Apart from one study on DPP4 activity in severe sepsis patients, the activity of these enzymes in sepsis patients have not been reported in the past." (PMID 32315321, 2020). "This is reassuring from the therapeutic point of view but tells us nothing about a possible value of DPP4 activity in plasma as a biomarker for sepsis." (PMID 32315321, 2020). "DPP4 activity has been shown to be decreased in the serum of patients with sepsis compared to healthy controls." (PMID 32315321, 2020).
Sepsis (continued). "In the following two subsections, we will present and discuss our recent findings on anti-inflammatory effects of SGLT-2 inhibitors, GLP-1 agonists, and DPP-4 inhibitors in animal models of diabetes type 1/2 as well as experimental sepsis." (PMID 31341533, 2019). "We compared changes in GLP-1R expression in the kidney among animals with sepsis, CKD, and CKD-with-sepsis; however, further studies of DPP-4 in sepsis are warranted." (PMID 31795376, 2019). "DPP-4 signaling cascade has been recently demonstrated to be involved also in the pathologic features of sepsis, mainly due to a selective cross-talk between DPP-4 and nuclear factor- kappa B (NF-κB) signaling pathways." (PMID 30619349, 2018). "The results obtained with GLP-1 supplementation and DPP-4 inhibition in models of endotoxemia are quite promising, but they remind us of the enthusiasm about statins as a new treatment strategy in sepsis and their failure in large clinical trials." (PMID 26251902, 2015). "Importantly, DPP4 inhibition also applied 6 h after sepsis induction prevented from sepsis-induced pulmonary edema." (PMID 40817204, 2025). "For instance, by detecting decreased DPP4 concentrations or increased TXN concentrations in patient sera, combined with clinical scores [such as the Sequential Organ Failure Assessment (SOFA) score], the early diagnostic efficiency for sepsis can be enhanced." (PMID 40124361, 2025). "Furthermore, some studies have reported a significant reduction in DPP4 expression in patients with sepsis and septic shock, while higher DPP4 expression correlates with improved patient survival." (PMID 40124361, 2025). "Sepsis per se induced changes to more than 4,000 differentially expressed genes (DEGs) in the murine endothelium with half of them upregulated upon DPP4 inhibition, while half of them were downregulated." (PMID 40817204, 2025). "To assess whether vascular protection by DPP4 inhibition translates into preserved organ function during sepsis, we analyzed integrity of murine liver and kidney." (PMID 40817204, 2025). "All-cause mortality, sepsis- and infection-related mortality, and mortality related to major adverse cardiovascular and cerebrovascular events were compared between patients treated with GLP-1 receptor agonists and patients treated with DPP-4 inhibitors." (PMID 35254430, 2022). "In summary, we observed lower all-cause mortality and sepsis-related mortality but not lower MACCE-related mortality in the GLP-1 receptor agonist group compared with the DPP-4 inhibitor group." (PMID 35254430, 2022). "On the other hand, dipeptidyl peptidase (DPP)-4 was reported to improve vascular dysfunction in an experimental sepsis model, although whether DPP-4 affects EndMT and fibrosis initiation during lipopolysaccharide (LPS)-induced lung injury is unclear." (PMID 29037205, 2017). "Interestingly, GLP-1 receptor agonists and DPP-4 inhibitors were found to similarly reduce mortality in inflammatory sepsis models." (PMID 26842302, 2016). "Others detected reduced oxidative stress under DPP-4 inhibitor therapy in animal models of type 1 diabetes, cardiac ischemia/reperfusion-injury, chronic myocardial infarction, abdominal aortic aneurysm, Parkinson’s diseases, and sepsis." (PMID 26251902, 2015). "In addition to their hypoglycemic effects, DPP-4 inhibitors have also been shown to exert anti-inflammatory and anti-atherosclerotic effects against cardiovascular diseases and an anti-inflammatory effect in experimental models of sepsis." (PMID 35328486, 2022). "This would provide us with the information whether the observed reduction in enzymatic activity in the most extreme form of sepsis develops gradually or at once and whether DPP4 and/or FAP should be used as a target to watch in patients with a high risk of developing sepsis." (PMID 32315321, 2020).
Sepsis (continued). "Expression validation revealed that DPP4 was predominantly highly expressed in the control group, while TXN exhibited elevated expression in the sepsis group." (PMID 40124361, 2025). "DPP4 and TXN were validated as biomarkers for sepsis, with insights into immune infiltration and therapeutic potential at the single-cell level, offering novel perspectives for sepsis treatment." (PMID 40124361, 2025). "DPP4 and TXN were identified as key biomarkers, showing higher expression in control and sepsis samples, respectively." (PMID 40124361, 2025). "Specifically, TXN was upregulated in the sepsis group, while DPP4 was elevated in the control group, positioning TXN and DPP4 as potential biomarkers." (PMID 40124361, 2025). "Exploration of immunomodulatory therapy: Single-cell analysis reveals high expression of DPP4 in CD4+ memory T cells, which are significantly depleted in sepsis." (PMID 40124361, 2025). "We demonstrated that DPP-4 inhibitors (linagliptin) and GLP-1 analogs (liraglutide) improved survival in sepsis." (PMID 34439423, 2021). "In experimental sepsis, the anti-inflammatory effects of GLP-1 analogs and DPP-4 inhibition were recently confirmed." (PMID 31341533, 2019). "The activity of ADA in the serum is increased during inflammatory diseases (e.g., sepsis) as a result of increased macrophages activity and the interaction of ADA with DPP-4 leads to NF-κB activation in T cells." (PMID 30619349, 2018). "More research is needed to better characterize the antioxidant and anti-inflammatory effects of DPP-4 inhibition and GLP-1 supplementation in the pathogenesis of sepsis." (PMID 26251902, 2015). "Two biomarkers, DPP4 and TXN, were identified and validated in the context of sepsis." (PMID 40124361, 2025). "Therefore, we plan to directly verify the roles of DPP4 and TXN in the pathogenesis of sepsis through gene knockout or overexpression experiments in the future and to explore their specific molecular mechanisms." (PMID 40124361, 2025). "A nested case-control study reported that hospitalisation for sepsis was not significantly different between cases and controls using DPP-4 inhibitors." (PMID 29047372, 2017). "In addition, we intend to combine in vitro cell models and animal experiments to further investigate the functions of DPP4 and TXN in pathways such as immune regulation and oxidative stress in order to gain a comprehensive understanding of their roles in sepsis." (PMID 40124361, 2025). "Although incretin-based therapies have not yet been tested in clinical trials of sepsis, it has been hypothesized that both incretin-mimetics and DPP4 inhibitors may exert positive pleiotropic effects on both inflammation and immunomodulation." (PMID 33973089, 2021). "We and others demonstrated that GLP-1 analogs like liraglutide and inhibitors of the enzyme dipeptidylpeptidase-4 (DPP-4), which rapidly degrades native GLP-1, ameliorate cardiovascular and thrombotic complications in animal models of lipopolysaccharide (LPS)-induced sepsis." (PMID 34439423, 2021). "Second, we could not compare the serum GLP-1 and DPP-4 levels between the sepsis and CKD groups because plasma GLP-1 is rapidly degraded by DPP-4, explaining why the change in serum GLP-1 level in sepsis cases based on the blood GLP-1 concentration is problematic." (PMID 31795376, 2019). "For instance, the high expression of TXN in CD16+ monocytes may affect the progression of sepsis by regulating the release of pro-inflammatory cytokines or the ferroptosis pathway, while the absence of DPP4 expression in memory CD4+ T cells may exacerbate immune suppression." (PMID 40124361, 2025). "DPP4, FAP and PREP are good in discriminating between septic shock patients and ICU controls and should be further explored to see whether they are already dysregulated in earlier stages, opening perspectives for their further investigation as biomarkers in sepsis." (PMID 32315321, 2020).
Sepsis (continued). "This study is the first to report a significant negative correlation between DPP4 and TXN in sepsis (r = −0.43, p < 0.05)." (PMID 40124361, 2025).
coronary artery disease (28 papers, 2013 to 2025). "Consistent with these recommendations, our study showed that in insulin-treated patients with T2D, GLP-1 RA use significantly reduced the risk of hospitalization for coronary artery disease compared with DPP-4 inhibitor and sulfonylurea use." (PMID 41011236, 2025). "Given the high risk of coronary artery disease in diabetic patients, the relevance of these potential effects of DPP-4 inhibitors on arrhythmias need to be tested in the clinical setting." (PMID 25388908, 2015). "Positive effects of DPP-4 inhibitors on the myocardium have also been described in patients with ischemic heart disease." (PMID 29787616, 2018). "Collectively, these findings indicate that increased blood DPP4 levels provide important information on angiographic severity, the extent of inflammation and coronary artery disease." (PMID 27654253, 2016). "Several polymorphisms have been described in the DPP4 gene (located in region 2q24.3), some of which have been associated with rheumatoid arthritis, T2DM, and myocardial infarction in patients with coronary artery disease (CAD)." (PMID 34178021, 2021). "A recent study reported that increased circulating DPP4 levels positively and independently associated with coronary artery disease, even in the absence of DM." (PMID 28587613, 2017). "Moreover, DPP4 protein has additional substrates that participate in responses to ischemic heart disease, such as stromal cell-derived factor-1 alpha (SDF1α), neuropeptide Y and substance P." (PMID 28587613, 2017). "The present results did not reveal any effects of GLP-1 agonists and DPP-4 inhibitors on the risk of angina and coronary artery disease in patients with T2DM." (PMID 29150631, 2017). "Therefore, in the present study we conducted a systematic review and network meta-analysis to comprehensively assess effects of the long-term use of GLP-1 agonists or DPP-4 inhibitors on ischemic heart diseases." (PMID 29150631, 2017). "However, until now it is unclear regarding the association between circulating DPP4 activity and coronary artery disease (CAD) in individuals with or without DM." (PMID 27654253, 2016). "Pre-specified factors for subgroup analyses are HbA1c, use of DPP-4 inhibitors, sex, body mass index, LDL-C, age, and the presence of treatment for existing ischemic heart disease." (PMID 29435776, 2018). "However, despite the overall negative association between DPP4 and coronary artery disease (CAD), several discrepancies have also been pointed out." (PMID 34389003, 2021). "A negative correlation between beclin-1 and DPP4 activity was observed in patients with coronary heart disease." (PMID 32340263, 2020). "However, the role of DPP4 in chronic heart failure, independent of coronary artery disease, remains unclear." (PMID 23853775, 2013).
acute kidney injury (26 papers, 2011 to 2025). Sudden and sustained deterioration of the kidney function characterized by decreased glomerular filtration rate, increased serum creatinine or oliguria. "For example, the increased risk of acute kidney injury observed in our study for initiators of DPP4 inhibitors vs. metformin is susceptible to residual and unmeasured confounding given metformin’s contraindication in patients with renal impairment." (PMID 30310100, 2018). "This suggested that DPP4 deficiency and remote ischemic preconditioning preserved renal function during acute kidney injury." (PMID 28903385, 2017). "Further studies are required to quantify the potential for within-class differences among DPP4 inhibitors, and to explore modifying factors with respect to the association between DPP4 inhibitors and acute kidney injury, acute respiratory tract infections, and acute pancreatitis." (PMID 30310100, 2018). "Furthermore, there is limited evidence evaluating the association between DPP4 inhibitors and acute outcomes, notably acute kidney injury and respiratory tract infections." (PMID 30310100, 2018). "Although we found an increased risk of acute kidney injury when comparing DPP4 inhibitor and metformin initiators, this comparison is highly susceptible to confounding by indication given metformin’s place in therapy and contraindication in patients with renal dysfunction." (PMID 30310100, 2018). "MERS-CoV uses dipeptidyl peptidase-4 (DPP4, also named CD26), a type-II transmembrane glycoprotein, as the cellular receptor to infect humans and cause severe respiratory disease and other severe complications, including renal failure and even multiorgan failure." (PMID 30646495, 2019). "We further detected that renal transcription level of DPP4 is positively correlated to the renal failure in the IgA patients according to their changes of serum creatinine and glomerular filtration rate, where an up-regulated KEGG pathway is related to DPP4." (PMID 40607249, 2025). "We found that prior DPP4 inhibitor use was associated with increased odds of in-hospital death, need for ICU, the occurrence of thromboembolic events, and acute kidney injury." (PMID 37374918, 2023). "Within the acute kidney injury cohort, there were 8,411 DPP4 inhibitor and 28990 sulfonylurea initiators." (PMID 30310100, 2018). "In decreased doses, DPP-4 inhibitors are considered safe in patients with moderate to severe renal failure." (PMID 28167928, 2017). "Moreover, the marked anti-inflammatory actions of linagliptin have been characterized in an endotoxin-induced acute kidney injury model, where DPP-4 inhibition inhibited NF-κB pathway and the downstream pro-inflammatory cytokines IL-1β and TNF-α." (PMID 35890148, 2022). "Cases of acute renal failure following treatment with DPP-4 inhibitors are rare." (PMID 32308645, 2020). "In T2DM patients with severe renal failure and HbA1cabove target, either a DPP4 inhibitor or a GLP-1RA (if eGFR 15–30 mL/min/1.73 m2) may be considered to improve blood glucose control." (PMID 32489427, 2020). "The risk of acute kidney injury was higher for current DPP4 inhibitor users, but not for recent or past users." (PMID 30310100, 2018). "Within 31,470 years of person-time follow-up this cohort experienced 288 episodes of acute kidney injury among new users of DPP4 inhibitors (n = 36, incidence rate = 4.8 per 1000 person-years) and sulfonylureas (n = 252, incidence rate 10.5 per 1000 person-years)." (PMID 30310100, 2018). "Consistent with findings from randomized controlled trials and prior observational research, our study suggests that DPP4 inhibitors do not increase the risk of acute kidney injury." (PMID 30310100, 2018).
acute kidney injury (continued). "A previous study showed that treatment with a GLP-1 receptor agonist or alogliptin, another DPP-4 inhibitor, attenuated cisplatin-induced acute kidney injury, and the knockdown of renal GLP-1 receptor expression in vivo by small interfering RNA reversed the renoprotective effects of alogliptin." (PMID 29317794, 2017). "This suggests that DPP4 inhibitors may contribute to the progression of renal failure." (PMID 39135967, 2024). "Similarly, our sensitivity analysis showed no significant increased or decreased risk of acute kidney injury found among users of DPP4 inhibitors." (PMID 30310100, 2018). "In addition, DPP-4 inhibitors ameliorated ischemia-reperfusion-induced acute kidney injury." (PMID 29317794, 2017). "In conclusion, our study demonstrates that DPP4 deficiency and remote ischemic preconditioning protect kidneys from acute IR injury by elevating circulating GLP-1 levels and represent potential therapeutic targets for acute kidney injury, especially in type 2 diabetic patients." (PMID 28903385, 2017). "Although the glucose lowering effect of dipeptidyl peptidase-4 (DPP4) inhibitors is well established, several potential serious acute safety concerns have been raised including acute kidney injury, respiratory tract infections, and acute pancreatitis." (PMID 30310100, 2018).